RETN (resistin)
Diseases named in the same sentence as RETN in open-access papers (continued):
Sharing a sentence is not in itself a finding about the gene and the disease.
inflammation (7 papers, 2007 to 2024). Aberrant reaction of the microcirculation characterized by movement of fluid and leukocytes from the blood into extravascular tissues. "Elevated serum leptin and resistin have also been associated with an increased burden of skin and joint inflammation." (PMID 30635024, 2019). "Another study found that elevated levels of resistin were prominent in patients with hepatobiliary inflammation and were associated with breach of self-tolerance; thus, resistin may be an important marker of disease severity in autoantibody-mediated gastrointestinal inflammatory diseases." (PMID 28061755, 2017). "Chronic inflammation from smoking affects endothelial function and may alter adipokine secretion, particularly resistin, in perivascular adipose tissue (PVAT)." (PMID 39635208, 2024).
bacterial infection (5 papers, 2012 to 2025). "A systematic review published in the World Journal of Hepatology highlights that presepsin, alongside resistin, demonstrates diagnostic performance comparable to procalcitonin in detecting bacterial infections among decompensated cirrhosis patients admitted to intensive care units." (PMID 40804836, 2025). "Other markers of bacterial infection, such as neutrophil gelatinase-associated lipocalin-2 (NGAL) and resistin, have shown promise across a range of clinical settings but have not been integrated in clinical practice yet." (PMID 34395340, 2021). "Our data suggest possible inter-relationships between pathways involving resistin, cytotoxic T cell activity and lipocalin-2, and a significant role for these proteins in the host defence against bacterial infection." (PMID 22559298, 2012). "However, resistin shows anti-inflammatory activity under the condition of bacterial infection or stimulation by bacterial products (LPS)." (PMID 34220862, 2021). "The primary aim of this study was to determine the discriminative ability of PCT, aPTT waveform, NGAL and resistin individually, in combination and compared to CRP to diagnose serious bacterial infection (SBI) in children on admission to PICU." (PMID 33544738, 2021). "Plasma concentrations of NGAL and resistin were significantly increased in children with confirmed SBI compared to children with no detectable bacterial infection (NBI), and to controls (287 versus 128 versus 62 ng/ml and 195 versus 90 versus 18 ng/ml, respectively, p < 0.05)." (PMID 22559298, 2012).
infectious disease (5 papers, 2015 to 2025). A disorder directly resulting from the presence and activity of a microbial, viral, or parasitic agent in humans. "While traditionally recognized as a pro-inflammatory cytokine expressed in immune cells that regulates chronic inflammatory, metabolic, and infectious diseases, emerging evidence reveals resistin's dual role as an innate immunity host defense peptide." (PMID 40636515, 2025). "Nonetheless, the ability of resistin to induce a Th1 response also explicates its role in infectious diseases via innate immune mechanisms." (PMID 26448186, 2015). "Both resistin (RETN) and stearoyl-CoA desaturase (SCD) are molecules that regulate lipid metabolism, and there are few studies on them in infectious diseases." (PMID 35059324, 2021).
aorta (3 papers, 2017 to 2025). "Further experimental studies may reveal the role of resistin in colorectal carcinogenesis." (PMID 28422056, 2017).
heart disease (3 papers, 2021 to 2025). "The consistent association between elevated circulating resistin levels and adverse clinical outcomes across a spectrum of cardiac diseases solidifies its prognostic value." (PMID 41347124, 2025). "Of note, regular physical activity significantly reduces the levels of resistin and high-density lipoprotein cholesterol, thus preventing inflammation and lowering the risk of heart disease." (PMID 33924645, 2021). "High resistin concentration increases the adiposity and accelerates the accumulation of low-density lipoprotein cholesterol (LDL-c) in arteries, increasing the risk of heart disease." (PMID 35053667, 2022).
immune disease (3 papers, 2016 to 2022). "Since previous reports indicated that resistin could suppress ROSs synthesis, we speculated that the reduction of serum resistin in uGD patients might increase ROS production and aggravate the immune disorders, which deserved further exploration." (PMID 27637079, 2016). "Thus, as both adipokine and inflammatory factor, human resistin is deserved to be investigated about the role it played in immune dysfunction and metabolism disorder of GD." (PMID 27637079, 2016).
connective tissue diseases (2 papers, 2012 to 2017). "Another interesting direction for a new treatment option for connective tissue disease is inhibiting the synthesis, release, and action of resistin by anti-resistin agents." (PMID 22584415, 2012).
inflammatory myopathies (2 papers, 2012 to 2016). "The exact role of resistin in muscle tissue regeneration or destruction in inflammatory myopathies needs further study." (PMID 22577940, 2012). "We have demonstrated that increased levels in tissue as well as serum concentration of resistin in patients with inflammatory myopathies correlate with global disease activity." (PMID 22577940, 2012). "The expression of resistin in muscle tissues from patients with inflammatory myopathies and healthy controls was evaluated." (PMID 22577940, 2012). "As we found increased systemic and local levels of resistin in inflammatory myopathies, we examined the effect of resistin on muscle and mononuclear cells in vitro." (PMID 22577940, 2012). "Serum resistin levels were determined in 42 patients with inflammatory myopathies and 27 healthy controls." (PMID 22577940, 2012). "We found that resistin expression in muscle tissues from patients with inflammatory myopathies was significantly higher when compared with control muscle tissues from patients with MG." (PMID 22577940, 2012). "In the present study, we consistently observed the up-regulation of resistin in the mononuclear cells of inflammatory infiltrates surrounding vessels and muscle fibres in patients with inflammatory myopathies." (PMID 22577940, 2012). "In our study, we observed a strong correlation between higher levels of serum resistin and CRP and, most importantly, we observed an association with the global disease activity assessment of inflammatory myopathy." (PMID 22577940, 2012). "Correlations between serum levels of resistin and disease activity in patients with inflammatory myopathies." (PMID 22577940, 2012). "The serum resistin levels were significantly higher in patients with inflammatory myopathies than in healthy controls (8.53 ± 6.84 ng/ml vs. 4.54 ± 1.08 ng/ml, P < 0.0001)." (PMID 22577940, 2012). "Therefore, we assessed the serum resistin level and its expression in muscle tissues from patients with idiopathic inflammatory myopathies and studied the potential role of resistin in the pathogenesis of muscle tissue damage." (PMID 22577940, 2012). "The increased expression of resistin was particularly localised in scattered mononuclear cells and in mononuclear cells in inflammatory infiltrates surrounding large vessels and muscle fibres in patients with inflammatory myopathies." (PMID 22577940, 2012). "Furthermore, up-regulation of resistin in muscle tissue and resistin-induced synthesis of pro-inflammatory cytokines in mononuclear cells suggest a potential role for resistin in the pathogenesis of inflammatory myopathies." (PMID 22577940, 2012). "Resistin expression in muscle tissue was significantly higher in patients with inflammatory myopathies compared to controls, and resistin induced the expression of interleukins (IL)-1β and IL-6 and monocyte chemoattractant protein (MCP)-1 in mononuclear cells but not in myocytes." (PMID 22577940, 2012). "Additionally, we found that the expression of resistin is up-regulated in muscle tissues of patients with inflammatory myopathies." (PMID 22577940, 2012). "The purpose of this study was to evaluate and compare the serum levels and local expression of resistin in patients with idiopathic inflammatory myopathies to controls, and to determine the relationship between resistin levels, inflammation and disease activity." (PMID 22577940, 2012). "Thus, resistin could play a potential role in the pathogenesis of inflammatory myopathies." (PMID 28076515, 2016). "That being said, resistin did not modulate the expression of several interferon (IFN)-α/β induced genes that have been recently observed in tissue of patients with inflammatory myopathies." (PMID 22577940, 2012). "In patients with inflammatory myopathies, but not in healthy controls, the serum resistin levels correlated with the CRP levels (r = 0.328, P = 0.040) and, interestingly, positively correlated with the global MYOACT score (r = 0.382, P = 0.026)." (PMID 22577940, 2012).
inflammatory myopathies (continued). "Thus, it could be hypothesized that serum resistin concentration may reflect global disease activity, including extramuscular organ involvement, rather than functional impairment in inflammatory myopathies." (PMID 22577940, 2012). "In contrast, resistin levels correlated neither with the creatine kinase and myoglobin levels nor with the MMT8 score in patients with inflammatory myopathies." (PMID 22577940, 2012).
peripheral vascular disease (2 papers, 2023 to 2024). Any disorder affecting blood flow through the veins or arteries outside of the heart. "Higher resistin levels are linked to a higher risk of major adverse cardiac events (MACE) in individuals with peripheral vascular disease (PAD)." (PMID 39558976, 2024). "Vascular disorders associated with angiogenesis may be significantly influenced by resistin." (PMID 39558976, 2024). "A decrease in GFR may be a consequence of a resistin-mediated vascular disorder, even in the early stages of atherosclerotic disease." (PMID 37623488, 2023).
musculoskeletal diseases (1 paper, 2018). "Furthermore, studies were largely being limited to leptin with little work evaluating other adipokines (adiponectin, resistin, adipsin, etc.)that are now actively being investigated in other musculoskeletal diseases." (PMID 29695079, 2018).
skeletal disease (1 paper, 2015). "Furthermore, an association between peripheral blood resistin gene expression and DM disease activity, including global, muscle, and extra-skeletal disease activity, was also seen." (PMID 25918482, 2015). "Furthermore, an association between peripheral blood resistin gene expression and DM disease activity, including global, muscle, and extra-skeletal disease activity was also observed." (PMID 25918482, 2015). "Furthermore, our study showed an association between peripheral blood resistin gene expression and DM disease activity, including global, muscle, and extra-skeletal disease activity." (PMID 25918482, 2015). "Moreover, baseline peripheral blood resistin gene expression significantly correlated with DM disease activity, including global, muscle, and extra-skeletal disease activity." (PMID 25918482, 2015).
RETN also shares sentences with these, for which no sentence is quoted: chronic periodontitis (13 papers); acute myocardial infarction (6); Cirrhosis (5); Hypercholesterolemia (5); unstable angina (5); gingivitis (4); hepatitis B (4); interstitial lung disease (4); essential hypertension (3); liver failure (3); peripheral artery disease (3); sleep apnea syndrome (3); allergic rhinitis (2); alopecia (2); arteriosclerosis (2); bladder cancer (2); cholestasis (2); colon polyps (2); fetal growth restriction (2); fibromyalgia (2); hypercortisolemia (2); juvenile idiopathic arthritis (2); lung disease (2); male infertility (2); multiple sclerosis (2); Neurodegeneration (2); psoriatic arthritis (2); relapsing-remitting MS (2); renal failure (2); respiratory failure (2).
A further 86 diseases each share a sentence with RETN in 2 papers or fewer.